PSMG2 (proteasome assembly chaperone 2)
Description:
Chaperone protein which promotes assembly of the 20S proteasome as part of a heterodimer with PSMG1. The PSMG1-PSMG2 heterodimer binds to the PSMA5 and PSMA7 proteasome subunits, promotes assembly of the proteasome alpha subunits into the heteroheptameric alpha ring and prevents alpha ring dimerization.
Synonyms: HCCA3; PAC2; TNFSF5IP1; MDS003; MGC15092; CLAST3; HsT1707; PRAAS4
Tractability: PROTAC: ubiquitination databases record sites on it; its protein half-life has been measured; a small molecule that binds it is known.
Gene: Protein-coding gene on chromosome 18 (12,658,043 to 12,728,945, forward strand). Ensembl gene ENSG00000128789.
Subcellular location: Nucleus
Subcellular location (Human Protein Atlas): Nuclear bodies; Nucleoplasm
Pathways (Reactome):
Metabolism of proteins: Proteasome assembly
Gene Ontology:
Molecular function: molecular adaptor activity; protein binding
Biological process: chaperone-mediated protein complex assembly; proteasome core complex assembly; proteasome assembly
Cellular component: nucleus; protein folding chaperone complex; cytosol
Genetic constraint (gnomAD): Loss-of-function variants: 10 observed, 21.51 expected, observed/expected ratio (o/e) 0.46, 90% interval 0.29 to 0.79. The upper end of that interval is the gene's LOEUF score, 0.79, which puts it in group 3 of 6, group 1 being the genes least tolerant of losing a copy. Missense variants: 257 observed, 260.42 expected, observed/expected ratio (o/e) 0.99, 90% interval 0.89 to 1.09. Synonymous variants: 95 observed, 89.21 expected, observed/expected ratio (o/e) 1.06, 90% interval 0.9 to 1.26.
Homologues: Orthologues: chimpanzee PSMG2 (99% identical), macaque PSMG2 (98% identical), dog PSMG2 (89% identical), mouse Psmg2 (88% identical), rabbit PSMG2 (84% identical), guinea pig PSMG2 (84% identical), tropical clawed frog psmg2 (59% identical), zebrafish psmg2 (53% identical), Drosophila melanogaster CG12321 (27% identical).
Diseases named in the same sentence as PSMG2 in open-access papers:
PSMG2 is named in the same sentence as 6 diseases in open-access papers, as found by Europe PMC text mining. Sharing a sentence is not in itself a finding about the gene and the disease. The quoted sentences say what the papers report.
breast carcinoma (1 paper, 2026). "The proteasome assembly chaperone (PSMG) gene family (comprised of PSMG1, PSMG2, PSMG3, and PSMG4) plays a critical role in proteasome biogenesis; however, its involvement in breast cancer remains poorly understood." (PMID 41869439, 2026).
head and neck cancer (1 paper, 2025). A primary or metastatic malignant neoplasm affecting the head and neck. "To explore the role of PSMG2 in tumorigenesis and the dedifferentiation process, we performed functional assays with the knockdown of PSMG2 in vitro and in vivo in two head and neck cancer cell lines." (PMID 40303289, 2025). "Here, we characterized the effect of PSMG2 downregulation on tumorigenesis and the dedifferentiation process in head and neck cancer cell lines." (PMID 40303289, 2025). "Notably, head and neck cancer exhibited a particularly marked difference in PSMG2 expression (p<0.001)." (PMID 40303289, 2025). "As shown in the bioinformatic analysis, tumors from patient samples exhibit elevated levels of this gene, suggesting that most head and neck cancer cell lines may already have saturated levels of PSMG2." (PMID 40303289, 2025). "In consequence, we explored the potential effects of decreasing PSMG2 expression on the tumorigenic capabilities of the RPMI-2650 and Detroit-562 head and neck cancer cell lines." (PMID 40303289, 2025).
lipodystrophy (1 paper, 2023). A congenital or acquired disorder characterized by abnormal loss or redistribution of the adipose tissue in the body. "The distinct roles in human diseases of PSMG2, on the other hand, were largely unknown, apart from the monogenic inheritance of CANDLE (chronic atypical neutrophilic dermatosis with lipodystrophy and elevated temperature) syndrome that was previously reported to occur of the PSMG2 mutations." (PMID 36619227, 2023).
cancer (3 papers, 2022 to 2025). A tumor composed of atypical neoplastic, often pleomorphic cells that invade other tissues. "Our findings showed a significant increase in PSMG2 expression within tumor tissues compared to normal tissues in most cancers examined (acronyms defined in File S1)." (PMID 40303289, 2025). "The TCGA database was employed to examine the differential expression of PSMG2 in normal adjacent tissues and tumor tissues across multiple cancer types." (PMID 40303289, 2025). "PSMG2 was involved in cancer metabolism-related pathways, including “GTP-XTP metabolism”, “ATP/ITP metabolism”, “Ubiquinone metabolism”, “Cell cycle_Role of APC in cell cycle regulation”, and “CTP/UTP metabolism”." (PMID 36619227, 2023). "For instance, seven PSM genes (i.e. PSMA1, PSMA4, PSMC1, PSMC3IP, PSMD13, PSMG2-3 (PSM class I/II/V)) were overexpressed in the majority of the 16 cancer types." (PMID 36123629, 2022). "The reduction of PSMG2 could disrupt these protective mechanisms, making cancer cells more vulnerable to therapeutic agents." (PMID 40303289, 2025).
tumor (1 paper, 2025). "Specifically, in HNSCC, PSMG2 is significantly overexpressed in tumor tissue, with its expression increasing as the tumor stage progresses and correlating with poorer overall survival, suggesting its potential oncogenic role." (PMID 40303289, 2025). "Moreover, PSMG2 expression exhibited a progressive increase with advancing tumor stage, demonstrating significant differences between stage I and the later stages (II, III, and IV)." (PMID 40303289, 2025). "Consistent with this, downregulation of PSMG2 in the HNSCC cell lines RPMI-2650 and Detroit-562 led to a significant reduction in proliferation in vitro and tumor growth in vivo, further supporting its potential as a prognostic biomarker and therapeutic target for these tumors." (PMID 40303289, 2025). "The absence of effects on tumor properties upon overexpression of PSMG2 may be due to the saturated expression levels of PSMG2 in our cell lines." (PMID 40303289, 2025).
PSMG2 also shares sentences with these, for which no sentence is quoted: autoimmune disease (1 paper).